RNU6-978P (RNA, U6 small nuclear 978, pseudogene)
Gene: Small nuclear RNA gene on chromosome 15 (19,883,614 to 19,883,716, forward strand). Ensembl gene ENSG00000201241.
Homologues: Orthologues: chimpanzee U6 (98% identical), macaque U6 (89% identical), dog U6 (68% identical), pig U6 (64% identical), rabbit U6 (63% identical), rabbit U6 (57% identical). Paralogues in human: RNU6-458P (97% identical), U6 (97% identical), RNU6-1293P (96% identical), RNU6-156P (96% identical), RNU6-1132P (94% identical), RNU6-614P (94% identical), RNU6-721P (93% identical), U6 (93% identical), RNU6-1207P (90% identical), RNU6-811P (90% identical), RNU6-452P (85% identical), RNU6-666P (85% identical), and 1287 more.